PHB2 (prohibitin 2)
Diseases named in the same sentence as PHB2 in open-access papers (continued):
Sharing a sentence is not in itself a finding about the gene and the disease.
hematologic tumor (1 paper, 2017). "siRNA mediated knockdown of PHB1 and PHB2 in Kit225 cells significantly enhanced their sensitivity to ROS-induced cell death, suggesting a protective function in human hematologic tumor cells." (PMID 29029444, 2017). "We provide novel evidence that PHB1 and PHB2 are upregulated in hematologic tumor cells to maintain mitochondrial integrity and protect against oxidative stress-induced cell death." (PMID 29029444, 2017). "Identifying the subcellular localization of PHB1 and PHB2 in hematologic tumor cells is important to understanding their function in hematologic cell transformation, as well as the general mechanism of action in normal human lymphocytes." (PMID 29029444, 2017). "Previous reports suggest PHB1 mRNA levels are inversely proportional to cellular proliferation in a number of cell types, however the results presented herein indicate PHB1 and PHB2 are upregulated during the oxidative stress response in hematologic tumor cells." (PMID 29029444, 2017).
PHB2 also shares sentences with these, for which no sentence is quoted: Arthritis (5 papers); Cerebral ischemia (3); non-small cell lung carcinoma (3); ankylosing spondylitis (2); Autoimmunity (2); breast (2); endometrial cancer (2); tuberculosis (2); acute myeloid leukemia (1); autoimmune disease (1); bacteremia (1); chronic lymphocytic leukemia (1); colitis (1); COVID-19 (1); Crohn disease (1); dilated cardiomyopathy (1); esophageal squamous cell carcinoma (1); fatty acid metabolic disorder (1); gastrointestinal infections (1); glomerulosclerosis (1); head and neck cancer (1); hepatitis B (1); immunodeficiencies (1); ischaemic heart disease (1); ischemia (1); kidney (1); lipodystrophy (1); liver cancer (1); liver fibrosis (1); liver steatosis (1).
A further 21 diseases each share a sentence with PHB2 in 1 paper.